IL6 (interleukin 6)
Diseases named in the same sentence as IL6 in open-access papers (continued):
Sharing a sentence is not in itself a finding about the gene and the disease.
Listeria infection (continued). "However, listeriosis patients with autoimmune diseases or miscarriages showed high levels of IL-17A/IL-6 ratios." (PMID 27965668, 2016). "In listeriosis, IL-6 production and STAT3 activation are initiated within the first hours p.i.." (PMID 23825949, 2013). "Therefore, high levels of Th2 cytokines (IL-6 or IL-10) seemed related with severe listeriosis." (PMID 27965668, 2016). "In a mouse Listeria monocytogenes infection model, it was observed that TLR2, responsible for the activation of MCs, plays a crucial role in regulating the synthesis of IL-6 and IL-13 during the innate immune response to this bacterium." (PMID 38638437, 2024). "In comparison to wild type mice, Prak-deficient mice showed increased levels of inflammatory cytokines and chemokines, including IL-6, TNF-α, IL-12 p70, MIP-1β and MCP-1, in the serum upon Listeria infection." (PMID 33936034, 2021). "While IL-12, IL-6 and IFNγ are all inducible by TNF, IL-18 is a cytokine upstream of TNF that has been described as playing a role in protection from Listeria infection." (PMID 29438281, 2018). "In this regard, all our patients developing neonatal listeriosis, had high titres of anti-GAPDH1-22 antibodies but low TNF-α/IL-6 ratios, confirming our efforts to formulate vaccines that increase Th1/Th2 ratios." (PMID 28903312, 2017). "We examined clinical cases of neonatal listeriosis in 2013–2015 and defined two useful prognostic immune biomarkers to design listeriosis vaccines: high anti-GAPDH1-22 titres and tumor necrosis factor (TNF)/interleukin (IL)-6 ratios." (PMID 28903312, 2017). "Production of IL-6 was significantly reduced after vaccination with DC-LLO91−99 or DC-GAPDH1−22, indicating that the classical acute inflammation in listeriosis was avoided with vaccination." (PMID 24600592, 2014). "Overall, α-IL6, STAT3 siRNA, and warfarin treatment further illustrated that CYLD impaired IL-6/STAT3-induced fibrin production resulting in impaired pathogen control and death from severe listeriosis." (PMID 23825949, 2013). "In vivo, CYLD also reduced hepatic STAT3 K63-ubiquitination and activation, NF-κB activation, IL-6 and NOX2 mRNA production as well as fibrin production in murine listeriosis." (PMID 23825949, 2013). "Activation of the IL-6/gp130/SHP2/MAPK pathway, which is also protective in listeriosis, induces p38-dependent PAI-1 production, which positively regulates fibrin deposition by inhibition of fibrinolysis." (PMID 23825949, 2013). "Listeria infection represses the constitutive expression of APP genes in hepatocytes and, importantly, this repression is maintained under conditions of inflammation, after stimulation with the pro-inflammatory cytokines IL-6 and IL-1β." (PMID 34858876, 2021). "Patients with neonatal listeriosis presented some biomarkers of poor prognosis, such as hypervirulent LM strains and low ratios of TNF-α/IL-6, as well as some biomarkers of better prognosis, such as high titres of anti-GAPDH1-22 antibodies and normal percentages of monocytes and CD8+ T cells." (PMID 28903312, 2017). "The repeated inhalation of such particles not only suppressed alveolar macrophages and T cell-mediated immune response to induced Listeria infection in rats, but also suppressed the in vitro production of IFN-γ, TNF-α, IL-1β and IL-6 by peripheral blood monocytes from healthy individuals." (PMID 26588473, 2015). "GRN-deficient mice failed to clear Listeria monocytogenes infection and allowed bacteria to proliferate, and also showed a substantial reduction in serum amounts of TNF-α and IL-6 upon administration of CpG-ODNs." (PMID 23755248, 2013). "In addition, CYLD reduced K63-ubiquitination and phosphorylation of STAT3 resulting in an impaired IL-6/STAT3-dependent production of fibrin by hepatocytes as well as fibrin deposition in the liver, which are also important for protection in listeriosis." (PMID 23825949, 2013).
Listeria infection (continued). "Production of Th1 cytokines MCP-1, TNF-α and IFN-γ and lack of production of Th2 cytokines such as IL-6 and IL-10, which are responsible for exaggerated inflammatory reactions and putative autoimmune responses in listeriosis, are features that are also relevant for protective DC vaccine vectors." (PMID 24600592, 2014). "We found that the production of proinflammatory cytokines, TNF-α, IL-6 and MCP-1, were impaired in the DUSP12 overexpressing cells, associated with reduced activations of p38 and JNK, but not ERK activation in response to LPS stimulation, BCG, and Listeria infection." (PMID 29062315, 2017). "Indeed, MHV68 infection did not enhance the transcription of Tnf, and only marginally enhanced the transcription of Il6 and Il12b even in control mice following Listeria infection, and did not rescue the defect in Tnf and Il6 induction observed in HOIL-1 KO mice." (PMID 25599590, 2015).
lymphoproliferative disorder (27 papers, 2007 to 2025). "MCD is a polyclonal lymphoproliferative disorder caused by hyperproduction of IL-6 in affected lymphoid tissues." (PMID 31951598, 2020). "MCD is a distinct type of lymphoproliferative disorder associated with inflammatory symptoms and IL-6 dysregulation." (PMID 27142509, 2016). "Similar to its viral counterpart, cellular IL6 (hIL6) has been also implicated in the pathogenesis of KSHV-associated lymphoproliferative disorders." (PMID 17957251, 2007). "Diagnostic criteria have been revisited, effective treatments have been identified (IL-1 (and IL-6) inhibition), as well as the risk of development of lymphoproliferative disorders, and novel genetic techniques have partially shed light on the pathophysiology of SchS." (PMID 25905009, 2014). "Multicentric Castleman disease (MCD) is a rare lymphoproliferative disorder accompanied by systemic symptoms characterized by polyclonal hypergammaglobulinemia and chronic inflammation due to overexpression of interleukin-6." (PMID 35212301, 2022). "Human herpervirus-8/human immunodeficiency virus negative Idiopathic multicentric Castleman disease (iMCD) is a lymphoproliferative disorder sustained by a pro-inflammatory condition of hypercytokinemia mostly mediated by Interleukin-6 (IL-6)." (PMID 33676575, 2021). "It is a lymphoproliferative disorder which is mediated by proinflammatory cytokines such as interleukin-6 (IL-6)." (PMID 31878962, 2019). "Treatment with an inhibitory anti-IL-6 antibody inhibited growth of LCLs in SCID mice, and remission was observed in 8/12 patients with post-transplant lymphoproliferative disorder upon treatment with the anti-IL-6 antibody." (PMID 29601503, 2018). "Hypothetically, the presence of mutant (myeloid) cells in the bone marrow of SchS patients produces high local concentrations of IL-1β and IL-6, facilitating the development of a lymphoproliferative disorder." (PMID 25905009, 2014). "Siltuximab is a human-mouse chimeric anti-IL-6 antibody approved in 2014 for HIV-negative and herpes virus-8 negative patients for the treatment of multicentric Castleman's disease, a lymphoproliferative disorder associated with increased IL-6 in the enlarged hyperplastic lymph nodes." (PMID 28083070, 2016). "Indeed, anti–IL-6 treatment has been successfully used in Castleman’s disease, a rare lymphoproliferative disorder." (PMID 25905009, 2014). "Moreover, dysregulated secretion of IL-6 has a pivotal role in lymphoproliferative disorders in an autocrine and paracrine cytokine stimulated manner, indeed, it contributes to the development of the auto-maintenance and neoplastic growth of EBV-immortalized B cells." (PMID 29456531, 2018). "Our results confirm that interleukin-6 (IL6) has a role in the COVID-19 disease and that anti-cytokine treatment can also be performed in patients with lymphoproliferative disorders." (PMID 36579547, 2022). "IL-1-targeted biologics have been expanding, as there are no known serious adverse effects such as lymphoproliferative disorder or virus reactivation like TNF or IL-6-targeting therapies." (PMID 31182982, 2019). "We designated these mice BCL2+IL6+AID− and found that they developed—with full genetic penetrance (100% incidence) and suitably short latency (93 days median survival)—a severe IgM+ lymphoproliferative disorder that recapitulated important features of human WM." (PMID 27813533, 2016).
plasmacytoma (27 papers, 2008 to 2025). Plasmacytoma is a localized mass of neoplastic monoclonal plasma cells that represents approximately 5% of all plasma cell neoplasms. "Elevated IL-6 levels are frequently observed in cases of extramedullary involvement, where IL-6 is thought to promote plasmacytoma development and proliferation of malignant plasma cells." (PMID 40757112, 2025). "A limitation of our study is the potential impact of pre-diagnostic treatments on baseline IL-6 measurements; some patients misdiagnosed as CIDP or solitary plasmacytoma received steroids or radiation before formal diagnosis." (PMID 40646134, 2025). "The concept that dysregulated IL-6 gene expression can initiate polyclonal plasmacytosis and subsequently lead to the development of a malignant monoclonal plasmacytoma is well supported by the available data." (PMID 38893662, 2024). "A decade later, other proteins previously known as hepatocyte stimulating factor, IFN-β2, as well as plasmacytoma growth factor were cloned and found to be identical to IL-6, first illustrating its pleotropic functionality." (PMID 37841263, 2023). "IL-11 was first identified in 1990, following the discovery of a protein factor that stimulated a murine plasmacytoma cell line previously thought to be IL-6 dependent." (PMID 32765502, 2020). "IL-6 was initially identified under several names in the 1980s as a protein involved in B-cell differentiation, a plasmacytoma growth factor, and a protein involved in the induction of acute phase proteins in the liver." (PMID 32765502, 2020). "Concomitant expression of MYC and deregulated IL-6 led to a more rapid plasmacytoma occurrence in a mouse model." (PMID 32329469, 2019). "Interleukin-6 (IL-6) seems to regulate both plasmacytoma development in BALB/c mice and oil granuloma formation in C57BL/6 mice during pristane-induced inflammation." (PMID 29201923, 2017). "(The ED50 for recombinant human IL-6 in the T1165.85.2.1 mouse plasmacytoma assay is 0.2–0.8 ng/ml, while it is 0.02–0.06 ng/ml for recombinant murine IL-6)." (PMID 21799891, 2011). "Finally, the Balb/c plasmacytoma line MPC11 has been reported to have an IAP LTR insertion upstream of Il6 resulting in its upregulated expression." (PMID 38714690, 2024). "Based on these premises, an IL-6 transgene (Tg) driven by the promoter of Ld gene of the major histocompatibility complex (H2-Ld) was generated in B6 mice and showed the development of massive policlonal plasmacytomas." (PMID 29732008, 2018). "To test this hypothesis, we examined the ability of conditioned supernatant from untreated and 4OHT-treated BCBL1-K13-ERTAM cells to support the survival of murine T1165 plasmacytoma cell line that requires IL6 for survival and proliferation." (PMID 22624040, 2012). "IL-6-deficient mice do not develop plasmacytoma, which aligns with this concept." (PMID 38893662, 2024). "We found that 29 patients were misdiagnosed as either chronic inflammatory demyelinating polyradiculoneuropathy (CIDP) or solitary plasmacytoma and received treatment prior to their formal diagnosis of POEMS syndrome and VEGF and IL-6 evaluations." (PMID 40646134, 2025). "Historically, IL-6 molecule had been studied under many different names such as B cell stimulatory factor-2 (BSF-2), IFN-β2, Hybridoma/plasmacytoma growth factor, hepatocyte-stimulating factor (HSF), until advancements in molecular testing." (PMID 31523783, 2019). "In another study with mouse plasmacytomas, i.e., tumors of mature plasma cells, EEF1A2 knockdown expression decreased IL-6-mediated activation of STAT3 and AKT pathways, leading to a decrease in proliferation of plasmacytomas (PCT) cell lines with delayed cell-cycle entry." (PMID 38172654, 2024). "Unlike the other cytokines tested here, IL6 was highly secreted by exposed patients' PBMCs; this was not surprising, since one of IL6's multi-functions is to stimulate hybridoma and plasmacytoma cell growth and help antibody production." (PMID 29868512, 2018).
plasmacytoma (continued). "Interestingly, when IL-6 Tg is stabilized in BALB/c background mice through progressive backcrossing until N20, derived c.IL6 mice spontaneously developed monoclonal plasmacytomas or B cell lymphomas within lymphoid tissues." (PMID 29732008, 2018). "c-myc rearrangement in IL-6 driven plasmacytomas was not an isolated finding in early transgenic studies of MM." (PMID 29732008, 2018).
psychological distress (27 papers, 2016 to 2026). "Exploratory analyses showed that, the association between the variant type of IL6 and the risk for RRIs was dependent on prenatal exposure to maternal psychological distress in males (OR 1.96; 95% CI 1.04–3.67)." (PMID 33828172, 2021). "For the GxE (maternal prenatal psychological distress) analyses, IL6 rs1800795 and IFI44L rs1333969 and rs273259 polymorphisms were selected based on their associations with RRIs (IL6 variants predisposing and IFI44L variants protecting)." (PMID 33828172, 2021). "Generally, we found ZSDS more suitable for the detection of the IL-6 polymorphism’s effect on mood disturbances." (PMID 26821321, 2016). "Also, a lower sense of coherence was associated with higher psychological distress and post-traumatic stress symptoms, while both a sense of coherence and IL-6 levels emerged as significant independent predictors of cortisol responses after controlling for age and work experience." (PMID 41595348, 2026). "Elevated levels of proinflammatory cytokines, such as interleukin-6 (IL-6) and tumor necrosis factor-alpha (TNF-α), are associated with altered sleep architecture, reduced melatonin production, and increased psychological distress." (PMID 40598531, 2025). "The top-ranked gene-sets detected by gene set enrichment analysis included those involved in IL-6 and PPAR signaling, both of which have been associated with MDD/psychological distress." (PMID 30705256, 2019). "There was also a near-significant association of psychological distress measured with the GHQ and pro-inflammatory IL-6 responses." (PMID 26294364, 2016). "Individuals with greater mood disturbances measured with the POMS following sedentary time displayed an heightened IL-6 response." (PMID 26294364, 2016). "Moreover, the onset of psychological distress in HCWs was related to early increases in astrocyte-specific levels of pro-inflammatory IL-6 and IFN-γ." (PMID 40917429, 2025). "Additionally, cognitive complaints correlated with inflammatory markers (IL-6) and all psychological distress measures, further supporting the link between psychosocial stress and cognitive function in TC patients." (PMID 41050387, 2025). "Higher rates of residence in low SES neighborhoods among Black/AA communities may lead to increased psychological distress, which has been reported to elevate levels of inflammatory markers such as interleukin 6 (IL-6)." (PMID 36139643, 2022). "Therefore, the hyperexpression of IL-6-related emotional dysregulation might act via central amygdala GABAergic dysfunctions." (PMID 38248262, 2024). "The hypothalamic–pituitary–adrenal axis could synthesize inflammatory mediators (e.g., IL-1, IL-6, and TNF-α) during psychological distress." (PMID 32410849, 2020). "Previous studies have shown that the experience of negative life events may result in increased levels of pro-inflammatory markers, mainly IL-6 and CRP, via psychological distress (Baumeister, Akhtar, Ciufolini, Pariante, & Mondelli, 2016; Flouri, Francesconi, Papachristou, Midouhas, & Lewis, 2019)." (PMID 39618323, 2024). "However, another study of individuals reporting psychological distress found no significant reduction of IL-6, TNF-α, and CRP post intervention or at follow-up." (PMID 35648793, 2022).
viral myocarditis (27 papers, 2013 to 2025). Myocarditis that is caused by an infection with a viral agent. "In a coxsackievirus B3 (CVB3) murine myocarditis model, nicotine activated α7nAChR, increased STAT3 phosphorylation, reduced the expression of TNF-α and IL-6, and attenuated the damage due to viral myocarditis." (PMID 39206262, 2024). "In viral myocarditis, continuous and excessive production of IL-6 will destroy the cytokine network and virus clearance, thus promoting myocardial damage." (PMID 35341142, 2022). "Overexpression of IL-6 in experimental animals subjected to viral myocarditis results in extensive myocardial inflammation, whereas IL-6 inhibition with tocilizumab reduced heart inflammation and infiltration with CD3+T-cells and CD68+ macrophages." (PMID 33833766, 2021). "Cardiomyocytes express IL-6, and recombinant IL-6 has been demonstrated to be cardioprotective in limiting viral myocarditis in mice." (PMID 32121587, 2020). "The proposed pathophysiology of viral myocarditis is based on activation of interleukin‐6 (IL‐6) and triggering of a subsequent cytokine storm, combined with direct myocardial injury." (PMID 32652713, 2020). "Among them, tumor necrosis factor (TNF)-α, interleukin (IL)-1, and IL-6 are the three representative proinflammatory cytokines of human and animal viral myocarditis." (PMID 28197102, 2017). "In acute viral myocarditis, activation of α7nAchR increases the phosphorylation of STAT3, reduces the levels of TNF-α and IL-6, and, ultimately, alleviates viral myocarditis." (PMID 25396421, 2014). "We also conclude that blocking α7nAchR reduces the phosphorylation of STAT3, increases the expression of TNF-α and IL-6, aggravating viral myocarditis." (PMID 25396421, 2014). "Because nicotine is a α7nAchR agonist and methyllycaconitine is a α7nAchR antagonist, we conclude that α7nAchR activation increases the phosphorylation of STAT3, reduces the expression of TNF-α and IL-6, and, ultimately, alleviates viral myocarditis." (PMID 25396421, 2014). "In agreement with previous studies from our and other laboratories, we found that carvedilol improved the survival of mice and reduced myocardial inflammation and necrosis in murine viral myocarditis by downregulating the production of IL-6 and TNF-α." (PMID 24225056, 2013). "However, the primary pathway active in influenza viral myocarditis is believed to be IL-1β, IL-6, and TNF-α dependent." (PMID 36851240, 2023). "IL-6 is of significance because elevated levels denote a poor prognosis in viral myocarditis." (PMID 36851240, 2023). "They found that α7 nAChR activation increases STAT3 phosphorylation, decreases TNF-α and IL-6 expressions, and ultimately reduces viral myocarditis, indicating that α7 nAChR agonists could be a promising new strategy for patients with viral myocarditis." (PMID 33425684, 2021). "IL-6 antibody blocks the Il-6 receptor and has been shown to be beneficial in viral myocarditis." (PMID 32198622, 2020). "In addition, IL-6 expression has been reported to be elevated in Coxsackievirus B3-induced mouse viral myocarditis and in acute aortic dissection patients." (PMID 33099539, 2020). "Moreover, the inhibition of α7nAchR reduces the phosphorylation of STAT3, increases the levels of TNF-α and IL-6, and, ultimately, aggravates viral myocarditis." (PMID 25396421, 2014). "Additionally, the administration of Ad-IL-17AR:Fc consistently reduced the systemic TNF-α and IL-6 production in the supernatants of the heart homogenates on day 90 post-infection in viral myocarditis." (PMID 23977238, 2013). "Although IL-6 may be essential in the process of virus antigen presentation, early activation of the immune response and weakening of virus replication seem to be significant in animal models of viral myocarditis." (PMID 35341142, 2022).